RPL27A (ribosomal protein L27a)
Description:
Component of the large ribosomal subunit. The ribosome is a large ribonucleoprotein complex responsible for the synthesis of proteins in the cell.
Synonyms: L27A; uL15
Tractability: Small molecule: an approved drug acts on it; a structure with a bound ligand is known; a high-quality ligand is known. PROTAC: ubiquitination databases record sites on it; its protein half-life has been measured; a small molecule that binds it is known. Other modalities: a drug acting on it is in phase 2 or 3 trials.
Target class: Other cytosolic protein
Gene: Protein-coding gene on chromosome 11 (8,682,732 to 8,714,759, forward strand). Ensembl gene ENSG00000166441.
Subcellular location: Cytoplasm
Subcellular location (Human Protein Atlas): Cytosol; Endoplasmic reticulum
Pathways (Reactome):
Metabolism of proteins: Eukaryotic Translation Termination; Formation of a pool of free 40S subunits; GTP hydrolysis and joining of the 60S ribosomal subunit; L13a-mediated translational silencing of Ceruloplasmin expression; PELO:HBS1L and ABCE1 dissociate a ribosome on a non-stop mRNA; Peptide chain elongation; Protein hydroxylation; Ribosome Quality Control (RQC) complex extracts and degrades nascent peptide; SRP-dependent cotranslational protein targeting to membrane; ZNF598 and the Ribosome-associated Quality Trigger (RQT) complex dissociate a ribosome stalled on a no-go mRNA
Metabolism of RNA: Major pathway of rRNA processing in the nucleolus and cytosol; Nonsense Mediated Decay (NMD) enhanced by the Exon Junction Complex (EJC); Nonsense Mediated Decay (NMD) independent of the Exon Junction Complex (EJC)
Cellular responses to stimuli: Response of EIF2AK4 (GCN2) to amino acid deficiency
Developmental Biology: Regulation of expression of SLITs and ROBOs
Disease: Viral mRNA Translation
Metabolism: Selenocysteine synthesis
Gene Ontology:
Molecular function: protein binding; RNA binding; structural constituent of ribosome
Biological process: cytoplasmic translation; negative regulation of myoblast fusion; spermatogenesis; striated muscle contraction; translation
Cellular component: cytoplasm; cytosol; cytosolic large ribosomal subunit; cytosolic ribosome; endoplasmic reticulum; membrane; nucleoplasm; large ribosomal subunit; ribosome
Genetic constraint (gnomAD): Loss-of-function variants: 0 observed, 18.03 expected, observed/expected ratio (o/e) 0, 90% interval 0 to 0.17. The upper end of that interval is the gene's LOEUF score, 0.17, which puts it in group 1 of 6, group 1 being the genes least tolerant of losing a copy. Missense variants: 118 observed, 197.31 expected, observed/expected ratio (o/e) 0.6, 90% interval 0.51 to 0.7. Synonymous variants: 69 observed, 69.52 expected, observed/expected ratio (o/e) 0.99, 90% interval 0.82 to 1.21.
Homologues: Orthologues: chimpanzee RPL27A (100% identical), mouse Rpl27a (97% identical), tropical clawed frog rpl27a (90% identical), Caenorhabditis elegans Y37E3.8 (68% identical), Drosophila melanogaster RpL27A (68% identical).
Diseases named in the same sentence as RPL27A in open-access papers:
RPL27A is named in the same sentence as 31 diseases in open-access papers, as found by Europe PMC text mining. Sharing a sentence is not in itself a finding about the gene and the disease. The quoted sentences say what the papers report.
breast carcinoma (8 papers, 2017 to 2024). "It exerts a targeted inhibition on the synthesis of RPL27A protein by affecting the synthesis of RPL27A mRNA, thereby promoting the proliferation, migration, and invasion of breast cancer cells." (PMID 38577588, 2024). "RPL27A, as one kind of large subunit RPs, belongs to the universal ribosomal protein uL15 family and is closely correlated with some cancers, such as breast cancer and colorectal cancer." (PMID 37474947, 2023). "For example, upregulation of RPL15 gene expression in breast cancer promotes massive metastasis and triggers enhanced translation of other ribosomal proteins, while inhibition of RPL27A hampers dissemination and invasive potential of breast cancer cells." (PMID 37958436, 2023). "RPL27A was one of the genes that are frequently co-expressed in breast cancer patients with RPS16, which was thought to be one of the targets of miR-7641." (PMID 34497807, 2021). "RPL27A was also one of the differentially expressed genes in the ribosome pathway involved in breast cancer using the Gibbs sampling approach." (PMID 34497807, 2021). "Our analytic results together with these reports indicated that RPL36 and RPL27A might be downstream key targets of LRRC75A-AS1/miR-3127-5p/miR-2114-3p pathways in breast cancer." (PMID 35145966, 2022). "RPL27A, a ribosomal subunit protein, has been well studied to conduct diverse responsibilities in multiple disease phenotypes; however, its functions in cancer, especially in breast cancers, have been rarely determined with a few exceptions." (PMID 34497807, 2021). "Among the ribosome protein genes, the RPL27A and RPL15 genes were upregulated in metastatic cancer cells with significant differences, which was consistent with the data in mouse breast cancer models." (PMID 34497807, 2021). "Finally, an inflammation-related ceRNA network in breast cancer at the single cell level was established based on lncRNA LRRC75A-AS1, miR-3127-5p, miR-2114-3p, RPL36 and RPL27A mRNAs." (PMID 35145966, 2022). "Therefore, RPL27A and TMCC2 might be two potential inflammation-related target genes of LRRC75A-AS1/miR-2114-3p pathway in breast cancer." (PMID 35145966, 2022).
Obesity (3 papers, 2014 to 2019). Accumulation of substantial excess body fat. "RPL27A encodes Ribosomal protein L27A, which has been linked to human obesity." (PMID 27322064, 2016). "The eSNP sources reside in genes CMYA5 and RPL27A which are obesity GWAS loci." (PMID 25210734, 2014).
colorectal cancer (2 papers, 2021 to 2023). A primary or metastatic malignant neoplasm that affects the colon or rectum. "High expression of the RPL27A gene will increase the risk of colorectal cancer." (PMID 34350180, 2021).
diabetes (1 paper, 2014). "Ontological classification demonstrates that these 14 genes are associated with diabetes (ALMS1P; RAET1L; GYS1; RBM47; EFR3B), cancer (RPL27A; SPAM1; PTCH1; ZNF277; USP35; CDC86), or metabolism (C3orf15; AOC2; GOT1)." (PMID 24885560, 2014).
metastatic cancer (1 paper, 2021). A carcinoma which has spread from the original site of growth to another anatomic site. "Consistent to its upregulation in metastatic cancer cells, knockdown of RPL27A significantly decreased the migration and invasion of the TNBC cell line, as well as other ribosome-related genes." (PMID 34497807, 2021). "Surprisingly, RPL27A was well colocalized with RPL15 only in metastatic cancer cells; however, in primary cancer cells, the transcripts of the two genes were low and rarely colocalized." (PMID 34497807, 2021).
schizophrenia (1 paper, 2015). A major psychotic disorder characterized by abnormalities in the perception or expression of reality. "This analysis demonstrated that the levels of eIF2α, RPL13, RPL13A, RPL18A, RPL27A and RPL32 were reduced in schizophrenia patient-derived cells in comparison with controls." (PMID 26485547, 2015).
triple-negative breast carcinoma (1 paper, 2022). An invasive breast carcinoma which is negative for expression of estrogen receptor (ER), progesterone receptor (PR), and human epidermal growth factor receptor 2 (HER2). "RPL27A was also found to be involved in development and metastasis of triple-negative breast cancer in both mouse and human." (PMID 35145966, 2022).
tumor (11 papers, 2011 to 2025). "We found that there were different expression levels of RPL27A in all tumor and peritumoral tissues in TMA." (PMID 37474947, 2023). "To validate the expression of Rpl27a in human TNBC tumor cells, we first accessed a published scRNA-seq data on primary human TNBC tumors." (PMID 34497807, 2021). "Notably, percentages of cells with Rpl27a expression among the four tumor models were comparable but were significantly higher than those of normal mammary epithelial cells of developmental stages." (PMID 34497807, 2021). "RPL27A is significantly upregulated in TNBC BM, through the activation of EIF2 signaling, thereby promoting tumor progression." (PMID 41259828, 2025). "Transcriptional profiles identified 39 genes that differentiated between 19 'metastatic' and 35 'non-metastatic' tumours, with molecular pathways involved in protein translation most strongly represented (MRPL33, RPL12, RPL27A, RPS5, RPS9)." (PMID 21385341, 2011).
cancer (9 papers, 2008 to 2025). A tumor composed of atypical neoplastic, often pleomorphic cells that invade other tissues. "We analyzed the expression of RPL27A in the pan-cancer analysis and analyzed the relationship between the expression of RPL27A and the clinical features and prognosis of patients with HCC." (PMID 37474947, 2023). "Altogether, these data suggested that the RPL27A gene is conducting critical functions in TNBC cancer development and metastasis and is a potential therapeutic target for TNBC." (PMID 34497807, 2021). "A more interesting gene was Rpl27a, which also showed significantly increased transcript in cancer cell and whose functions had rarely been studied in diseases or cancers." (PMID 34497807, 2021). "Surprisingly, two ribosomal protein genes, Rpl27a and Rpl15, were significantly upregulated in the cancer cells in all the TNBC models." (PMID 34497807, 2021). "The transcripts of Rpl27a in split violin plots and UMAPs further confirmed the significantly upregulated transcription in cancer cells of all the cancer models compared to normal epithelial cells in all the mammary developmental stages." (PMID 34497807, 2021). "In the pan-cancer analysis based on the TCGA database, we used TIMER to study the role of RPL27A in immune infiltration." (PMID 37474947, 2023). "Ribosomal protein genes, represented by RPL27A and RPL15, showed significantly upregulated expression in metastatic TNBC cancer cells." (PMID 34497807, 2021). "Among the deregulated gene candidates, ribosome protein genes were highly involved in TNBC development and metastasis, and two of the most consistent genes between mouse models and human cancer were RPL15 and RPL27A." (PMID 34497807, 2021). "Three of these antigens are encoded by unknown genes (Pr3, Pr6 and Pr Pr52 respectively); additionally three of them (Pr8-ribosomal protein L27a, Pr16-MTA1 and Pr31-ribosomal protein S10) have previously been reported to be over-expressed in cancer." (PMID 18949081, 2008). "Recent studies have shown that RPL27A could be used as a biomarker for a variety of cancers, but its role in HCC is not clear." (PMID 37474947, 2023).
infection (6 papers, 2008 to 2023). The state of being infected such as from the introduction of a foreign agent such as serum, vaccine, antigenic substance or organism.
RPL27A also shares sentences with these, for which no sentence is quoted: acute lymphoblastic leukemia (1 paper); breast invasive carcinoma (1); cholangiocarcinoma (1); colon adenocarcinoma (1); esophageal carcinoma (1); gangrene (1); glioblastoma (1); head-neck squamous cell carcinoma (1); herpesvirus infections (1); kidney chromophobe (1); lung adenocarcinoma (1); lung squamous cell carcinoma (1); melanoma (1); metastatic melanoma (1); multiple myeloma (1); ovarian carcinoma (1); prostate adenocarcinoma (1); rectum adenocarcinoma (1); T-cell acute lymphoblastic leukemia (1); thymoma (1); uterine corpus endometrial carcinoma (1).